PRSS48 (serine protease 48)
Synonyms: ESSPL
Tractability: Antibody: UniProt places it where antibodies can reach, with high confidence; UniProt predicts a signal peptide or a membrane-spanning region; its Gene Ontology location is reachable by antibodies, with medium confidence.
Gene: Protein-coding gene on chromosome 4 (151,277,161 to 151,291,862, forward strand). Ensembl gene ENSG00000189099.
Subcellular location: Secreted
Gene Ontology:
Molecular function: protein binding; serine-type endopeptidase activity
Biological process: proteolysis
Cellular component: extracellular region
Genetic constraint (gnomAD): Loss-of-function variants: 22 observed, 27.17 expected, observed/expected ratio (o/e) 0.81, 90% interval 0.58 to 1.16. The upper end of that interval is the gene's LOEUF score, 1.16, which puts it in group 5 of 6, group 1 being the genes least tolerant of losing a copy. Missense variants: 373 observed, 405.8 expected, observed/expected ratio (o/e) 0.92, 90% interval 0.84 to 1. Synonymous variants: 149 observed, 151.96 expected, observed/expected ratio (o/e) 0.98, 90% interval 0.86 to 1.12.
Homologues: Orthologues: macaque PRSS48 (92% identical), chimpanzee PRSS48 (87% identical), rabbit PRSS48 (64% identical), pig PRSS48 (62% identical), guinea pig PRSS48 (61% identical), rat Prss48 (59% identical), dog PRSS48 (59% identical), mouse Prss48 (57% identical), zebrafish zgc:100868 (36% identical), zebrafish zgc:123217 (29% identical), zebrafish si:ch73-182e20.3 (29% identical), zebrafish si:dkeyp-93a5.3 (27% identical), and 1 more. Paralogues in human: PRSS27 (34% identical), PRSS33 (31% identical), OVCH1 (30% identical), TMPRSS12 (30% identical), PLAT (28% identical), PLG (28% identical), PRSS50 (26% identical), KLK15 (24% identical), KLK9 (23% identical), GZMM (22% identical), PRSS57 (21% identical), PRSS37 (18% identical), and 2 more.
Diseases named in the same sentence as PRSS48 in open-access papers:
PRSS48 is named in the same sentence as 3 diseases in open-access papers, as found by Europe PMC text mining. Sharing a sentence is not in itself a finding about the gene and the disease. The quoted sentences say what the papers report.
Azoospermia (1 paper, 2025). Absence of any measurable level of sperm,whereby spermatozoa cannot be observed even after centrifugation of the semen pellet. "PRSS48 was identified to be highly and specifically expressed in the testes and significantly different in non-obstructive azoospermia (NOA) patients compared with healthy Controls." (PMID 41373827, 2025).
viral infections (1 paper, 2021). "The serine protease 48 (PRSS48) and SH3 domain-containing 19 (SH3D19) genes do not have known functions relating to viral infections or respiratory illness." (PMID 34409086, 2021).
PRSS48 also shares sentences with these, for which no sentence is quoted: infection (1 paper).